PPP1R36 (protein phosphatase 1 regulatory subunit 36)
Description:
Inhibits phosphatase activity of protein phosphatase 1 (PP1) complexes.
Synonyms: C14orf50
Tractability: No criterion of Open Targets' tractability assessment is met for any kind of drug.
Gene: Protein-coding gene on chromosome 14 (64,549,918 to 64,589,384, forward strand). Ensembl gene ENSG00000165807.
Gene Ontology:
Molecular function: phosphatase binding
Genetic constraint (gnomAD): Loss-of-function variants: 22 observed, 27.24 expected, observed/expected ratio (o/e) 0.81, 90% interval 0.58 to 1.15. The upper end of that interval is the gene's LOEUF score, 1.15, which puts it in group 5 of 6, group 1 being the genes least tolerant of losing a copy. Missense variants: 326 observed, 374.82 expected, observed/expected ratio (o/e) 0.87, 90% interval 0.79 to 0.95. Synonymous variants: 111 observed, 123.84 expected, observed/expected ratio (o/e) 0.9, 90% interval 0.77 to 1.05.
Homologues: Orthologues: chimpanzee PPP1R36 (99% identical), dog PPP1R36 (80% identical), guinea pig PPP1R36 (73% identical), pig PPP1R36 (73% identical), mouse Ppp1r36 (70% identical), rat Ppp1r36 (67% identical), rabbit PPP1R36 (67% identical), Drosophila melanogaster CG31391 (19% identical), Drosophila melanogaster CG31467 (17% identical), Drosophila melanogaster CG14689 (16% identical).
Diseases named in the same sentence as PPP1R36 in open-access papers:
PPP1R36 is named in the same sentence as 3 diseases in open-access papers, as found by Europe PMC text mining. Sharing a sentence is not in itself a finding about the gene and the disease. The quoted sentences say what the papers report.
Azoospermia (1 paper, 2022). Absence of any measurable level of sperm,whereby spermatozoa cannot be observed even after centrifugation of the semen pellet. "Thus, the present study, in relation to the individual previous studies, aims to identify SPA17, PPP1R36, AURKA, TRIP13, PLK4, CCDC90B, and CCDC91 genes as important biomarkers of both teratozoospermia- and azoospermia-associated infertility in men." (PMID 36292606, 2022).
PPP1R36 also shares sentences with these, for which no sentence is quoted: Infertility (1 paper); teratozoospermia (1).